CD4 (CD4 molecule)
Diseases named in the same sentence as CD4 in open-access papers (continued):
Sharing a sentence is not in itself a finding about the gene and the disease.
Opportunistic infection (continued). "Additionally, few or no studies have analyzed the possible role of LLV with drug resistance as a tool to predict CD4 cell count < 200 cells/μL, while patients who initiate ART with a CD4 > 200 cells/μL are at reduced risk of death and serious opportunistic infections." (PMID 35509014, 2022). "Furthermore, an association between higher BMI and higher CD4 counts was reported in a past study, which may lessen the likelihood of acquiring an opportunistic infection." (PMID 32398924, 2020). "As age progresses, more diseases and more medications are observed, mainly in patients within the profile of our study, most of them hospitalized with severe immunodeficiency (T CD4 lymphocytes <200), which may cause the emergence of opportunistic infections, requiring prophylaxis." (PMID 31460617, 2019). "However, despite this “treat all” recommendation, CD4 testing remains important for establishing baseline immune function and identifying patients with advanced HIV disease (defined as CD4 T-cell count below 200 cells/μl), who are at higher risk for opportunistic infections (OIs)." (PMID 30794637, 2019). "Therefore, correlation between low CD4 and DVT was significant even after correcting for immobility which may be associated with higher rates of opportunistic infections in people with low CD4 counts." (PMID 29370816, 2018). "Besides the small numbers, this might be due to the fact that patients who received ART were also those at highest risk of dying (because they had low CD4 counts or other opportunistic infections)." (PMID 27198545, 2016). "Furthermore, for patients who are presenting late to care, a CD4 count is required as a baseline measurement to identify the need for screening and prophylaxis for major opportunistic infections which are often associated with low CD4 count and increased risk of mortality." (PMID 27769181, 2016). "Similarly, in a cohort of 2,348 HIV-positive patients from the United States, severity grades of anemia were associated with an increased mortality risk, after controlling for CD4 cell count, age, antiretroviral treatment and development of opportunistic infections." (PMID 25005803, 2014). "However patients with low CD4 count are more likely to take longer to return to normal CD4 count levels, and may remain at increased risk of opportunistic infection hence morbidity." (PMID 24013838, 2013). "The finding of increased percentages of CD4+ T cells expressing FOXP3 in HIV infected individuals suggests that an imbalance of regulatory to effector T cells could be responsible for susceptibility to opportunistic infection." (PMID 20668701, 2010). "Since patients with SO-CD4 at 6 months are likely to maintain the phenomenon, they may need evaluation of the recovery of CD4 cell function, more so in Africa where there is an increased background risk of opportunistic infections." (PMID 18957083, 2008). "Untreated HIV infection leads to CD4+ T-cell depletion and severe immune dysfunction, resulting in opportunistic infections, neoplastic changes, and death." (PMID 41677609, 2026). "Median time from CD4 testing to receipt of opportunistic infection screening was 0 days (IQR 0−0) in both arms." (PMID 41566892, 2026). "There was a trend towards fewer severe adverse events, hospitalizations and opportunistic infections in the Visitect CD4 arm." (PMID 41566892, 2026). "A substantial proportion of hospitalized patients present with low CD4 lymphocyte count, opportunistic infections, or complications that arise from treatment interruption or untreated HIV infections." (PMID 41939633, 2026). "Patients in the low CD4 count group showed more opportunistic infections, organ injury markers, and therapeutic interventions." (PMID 41601726, 2026). "Other known factors that influence the measurement of HbA1c in PLWHIV are: a CD4+ T cell count < 500 cells/μL, drugs against opportunistic infections, like dapsone and ribavirin, and the presence of HCV." (PMID 39940683, 2025).
Opportunistic infection (continued). "From the longitudinal submodel, age, time, baseline CD4, educational level, occupation, adherence, WHO stage, social support, TB status, opportunistic infection, and body mass index were significantly related to CD4 cell count." (PMID 40260411, 2025). "This potentially reflects a broader pattern, where older individuals experienced a different virological and treatment landscape, having initiated ART later, with lower nadir CD4+ T cell counts and a higher incidence of opportunistic infections." (PMID 41216424, 2025). "This condition is typically seen in patients of African descent and in patients with HIV who either have an opportunistic infection or a CD4 count of less than 200 per cubic millimeter." (PMID 40718301, 2025). "The study showed that sex, opportunistic infections or AIDS-defining cancers, CD4 count, and social support were significantly associated with depression." (PMID 40485941, 2025). "Anxiety in PLWHIV is often precipitated by critical moments in their clinical journey, including the initial diagnosis, the onset of illness due to opportunistic infections, a declining CD4+ T-cell count, or an increasing HIV-1 viral load." (PMID 41295583, 2025). "Infections like HIV-1, which deplete CD4+ T cells, lead to profound immunodeficiency, leaving the host vulnerable to opportunistic infections and malignancies." (PMID 40004169, 2025). "The management of ICL patients is aimed at treating and/or preventing opportunistic infections and increasing the number of CD4 T-cells." (PMID 39866372, 2025). "In our population mainly composed of immunocompromised patients with < 200 CD4/mm3, in a region with high histoplasmosis and tuberculosis endemicity, opportunistic infections and malignancy were more than twice as common as benign causes." (PMID 40982488, 2025). "Over time, this process depletes the body’s CD4+ T-cells, weakening the immune system and leaving the individual vulnerable to opportunistic infections." (PMID 40071324, 2025). "Even in the “treat all” ART era, CD4+ counts remain essential for staging and prophylaxis against opportunistic infections." (PMID 41374357, 2025). "Mpox is an opportunistic infection that can cause severe disease in PWH, particularly those with advanced HIV, along with low CD4 counts." (PMID 41216051, 2025). "However, it is important to note that more than 80% of PLwHIV reach CD4 levels of ≥350 cells/μL, which is already considered a clinically favorable immunological state for PLwHIV, associated with a significantly lower risk of opportunistic infections and improved long-term outcomes." (PMID 40560021, 2025). "For example, HIV-1 specifically targets CD4+ T cells, inducing cell death and leading to acquired immunodeficiency syndrome, which is characterized by recurrent opportunistic infections and malignancies." (PMID 40004169, 2025). "During the 2006–2009 period, HIV-infected individuals were only eligible to start ART once they met specific immunological or clinical criteria, such as a significant drop in CD4 count or the onset of opportunistic infections." (PMID 40428272, 2025). "Stage 3 of HIV infection, when the immune system of a person living with HIV becomes severely compromised (measured by CD4 cell count) and/or the person becomes ill with an opportunistic infection." (PMID 40842718, 2025). "A recently published WHO policy brief addressing the management of opportunistic infections in AHD supports CD4 testing to detect AHD and determine eligibility for CTX prophylaxis." (PMID 40158188, 2025). "With progression to HIV, PLWH develops different types of opportunistic infections due to decreased T-lymphocytes with subsequent decreased in CD4 cell counts." (PMID 39834358, 2025). "Limited access to CD4 + T-cell count monitoring and opportunistic infection management complicates treatment, highlighting the importance of integrated mpox–HIV care models and vaccine safety studies for people with weakened immune systems." (PMID 41414936, 2025).
Opportunistic infection (continued). "In patients with CD4+ counts below 200 cells/μL, opportunistic infections such as TE, PCNSL, and tuberculomas dominate the differential, along with progressive multifocal leukoencephalopathy (PML)." (PMID 39906422, 2025). "The CD4 count of 61.1% of the study participants was below 200 cells/mm3, and 36.6% of the participants had experienced opportunistic infections." (PMID 40485941, 2025). "This case highlights that cryptococcal meningitis can occur even in patients with relatively high CD4+ counts for an opportunistic infection." (PMID 41209902, 2025). "These include supporting laboratory tests (e.g., viral load and CD4 count), visit to infectious disease physicians, and care and treatment for opportunistic infections." (PMID 40512690, 2025). "The multivariate binary logistic regression model revealed that sex, opportunistic infection, CD4 count, and level of social support were statistically significantly associated with depression in patients on HAART at Okugu Refugee Camp (p-value <0.05)." (PMID 40485941, 2025). "For liver transplantation, the recommended CD4 + count threshold is > 100 cells/μL because splenomegaly can lower absolute CD4 T cell count and > 200 cells/μL for those with a history of an opportunistic infection." (PMID 40113607, 2025). "Both instruments were associated with variables such as economic status, smoking habits, disease stage, opportunistic infections, CD4 T-cell count, sarcopenia construct, handgrip strength, and gait speed." (PMID 39752996, 2025). "Sarcopenia risk, as determined by both tools, was higher in low-income PLHIV with opportunistic infections, CD4 T-cell count ≤ 200 cells/mm3, low HGS, and low GS, and lower in asymptomatic and non-smoking individuals." (PMID 39752996, 2025). "A CD4+ T cells count < 100 cells/μL represents a critical threshold for opportunistic infections and complex co-infections." (PMID 41488483, 2025). "With the success of ART, PWH are now living longer with higher CD4+ cell counts and fewer opportunistic infections." (PMID 39459894, 2024). "CD4 count plays a vital role in immune function, protecting the body against opportunistic infections and multiplication of the virus." (PMID 38654969, 2024). "With a low CD4 count, concern for opportunistic infections was warranted, especially given his chest X-ray findings." (PMID 39439637, 2024). "Other non-antiretroviral factors that have been associated with SD in HIV-infected men include age, sexual preference, duration of HIV infection, CD4 T-cell nadir and the occurrence of opportunistic infection." (PMID 38451991, 2024). "CD4 count remains a reliable measure for clinical staging and treatment decisions, alongside identifying opportunistic infections (OIs)." (PMID 39569255, 2024). "CD4+ is a marker of the severity of HIV-associated immunodeficiency, and low CD4+ counts lead to increased mortality and morbidity as well as opportunistic infections." (PMID 39338313, 2024). "This leads us to discussing the importance of screening for HIV which would then lead us to clues for opportunistic infections based on patients’ symptoms after obtaining a CD4 count." (PMID 39439637, 2024). "Herein, we report a male patient with recurrent opportunistic infections, reduced CD4+ T and B lymphocyte counts, and hypoimmunoglobulinemia, which ultimately proved PID by genetic testing." (PMID 39823049, 2024). "The multivariate analyses indicated that both CD4+ T-cell counts and lymphocyte counts were significant predictors of opportunistic infections." (PMID 39866736, 2024). "In fact, CD4 cell count at ART initiation is the most significant predictor of disease development and dictates opportunistic infection (OI) risk categorization." (PMID 38926656, 2024). "Several studies have shown that anemia in HIV patients is closely related to low CD4 +T lymphocyte levels, advanced stage of the disease, opportunistic infections, as well as age and sex." (PMID 39330902, 2024).
Opportunistic infection (continued). "Safety has yet to be established in those with depressed CD4+ T cell counts or suffering from opportunistic infections." (PMID 38194272, 2024). "Our patient aligned with this data, presenting with advanced immunosuppression (CD4 count of 63 cells/μL) and multiple concomitant opportunistic infections." (PMID 39749085, 2024). "In a bivariate logistic regression analysis, variables like age, place of residency, marital status, WHO clinical staging, CD4 count, isoniazid plus rifapentine prophylaxis, CPT, and other opportunistic infections were associated with the occurrence of TB." (PMID 38638270, 2024). "HIV patients become more vulnerable to opportunistic infections, such as disseminated forms of M. avium and M. intracellulare, as CD4 lymphocyte counts drop below 200/mm3." (PMID 39640097, 2024). "So, starting ART/cART as soon as possible is related to a better recuperation of CD4+ T-cell counts and, consequently, to the reduction in problems caused by HIV immunosuppression—such as opportunistic infections and malignant neoplasms." (PMID 39452163, 2024). "In our study, 77% of patients had CD4 counts less than 100 cells/mm3, and the majority of patients were coinfected with bacterial and opportunistic infections." (PMID 38170073, 2024). "Higher CD4 counts lead to slower disease progression, fewer opportunistic infections, improved quality of life, and increased lifespan." (PMID 39022519, 2024). "It was anticipated that only a small proportion of patients would present with a baseline CD4 count ≤ 200 cells/m3 and/or manifestations of opportunistic infections." (PMID 38299523, 2024). "Poor adherence to ART drugs, opportunistic infection, CD4 count < 100cells/mm3 at switch, and advanced WHO clinical stage III/IV at switching were identified as risk factors for second-line ART failure." (PMID 38652716, 2024). "HIV is a virus that attacks the immune system, specifically targeting CD4+ T cells and progressively weakening the host’s ability to protect itself from opportunistic infections." (PMID 38494500, 2024). "Variables with a p-value of <0.25 in the bivariate Cox regression analysis, such as sex, age, residence, BMI, WHO clinical stage, adherence, CPT, IPT, baseline CD4, and past opportunistic infection, were included in the multivariate Cox regression model." (PMID 39529713, 2024). "Adherence to ART, body mass index, baseline CD4 count, disclosure, opportunistic infections, and baseline viral load count were identified as significant contributing factors to virological suppression." (PMID 38654969, 2024). "In patients with late-stage HIV infection, CD4+ T cells are severely depleted, and opportunistic infections by Mycobacterium tuberculosis, cytomegalovirus, fungi, and other pathogens are the primary causes of prolonged fever." (PMID 39081273, 2024). "Individuals testing RTRI-recent with CD4 counts <200 cells/mm3 or those having opportunistic infections were classified as RITA-CS-long-term." (PMID 39724047, 2024). "Food insecurity is linked to HIV-related mortality among PLHIV, partial HIV RNA suppression, long-term CD4 cell decline, increased opportunistic infections, and hospitalizations." (PMID 38907324, 2024). "A diagnosis of PID should be suspected in patients with recurrent opportunistic infections, decreased CD4+ T and B lymphocyte, and hypoimmunoglobulinemia when secondary immunodeficiency factors can be excluded." (PMID 39823049, 2024). "HIV-1, the predominant strain, primarily targets and depletes CD4+ T cells, leading to immunodeficiency and subsequent vulnerability to opportunistic infections." (PMID 39599797, 2024). "The risk for development of IRIS increases with lower levels of CD4 cells at baseline, the presence of opportunistic infections–especially TB–and with earlier initiation of ART if opportunistic infections are present." (PMID 38330045, 2024).
Opportunistic infection (continued). "Having opportunistic infections, CD4 levels below threshold, and any stage of educational level or residence were unrelated to the probability of nutritional recovery." (PMID 38261563, 2024). "Lower CD4+ T cell count and higher viral loads are generally associated with more advanced stages of HIV infection and increased risk of opportunistic infections and other complications." (PMID 38494500, 2024). "A diagnosis of PID should be suspected in patients with recurrent opportunistic infections, reduced CD4+ T and B lymphocyte counts, and hypoimmunoglobulinemia in the conditions that secondary immunodeficiency factors were excluded." (PMID 39823049, 2024). "HIV patients with low CD4 count and severe immunodepression can develop neuropathy also from opportunistic infections, and responsible pathogens include CMV, EBV, herpes simplex virus, and varicella‐zoster virus." (PMID 38813755, 2024). "All participants newly discovered to live with HIV presented a low CD4+ count (median number of 21 cells/μL) and concomitant opportunistic infections (i.e., Pneumocystis jirovecii pneumonia and disseminated cytomegalovirus infection)." (PMID 37760757, 2023). "Opportunistic infections commonly affect people with HIV with very low CD4 counts (<200 cells/mm3) due to progressive immune suppression." (PMID 37351535, 2023). "The results presented in this research contribute to a broader understanding of the impact of HIV infection on pulmonary health and offer insights into the role of factors such as CD4 count category, viral load, and opportunistic infections." (PMID 38022158, 2023). "Further exploration into differences in care-seeking behaviors; coverage of screening, prophylaxis, and/or treatment of opportunistic infections; and more extensive testing options for men to include CD4 is recommended." (PMID 37805465, 2023). "Despite the severely decreased CD4+-T-cells, only one opportunistic infection (herpes zoster-reactivation) occurred during the observation period." (PMID 37152008, 2023). "HIV destroys the CD4 cells, weakening a person’s immunity against opportunistic infections, such as tuberculosis and fungal infections, severe bacterial infections and some cancers." (PMID 37214076, 2023). "ART for HIV-infected children leads to immunological reconstitution through decreasing viral load, increasing CD4 cells, preventing opportunistic infection, and a longer survival time." (PMID 37471340, 2023). "The progression of HIV-1 infection to AIDS is characterized by the increased presence of opportunistic infections as CD4+ counts decline." (PMID 37108634, 2023). "Recent CD4 count, opportunistic infection, antiretroviral therapy regime at initiation, and anti-retroviral therapy regime change were significantly associated with musculoskeletal disorder." (PMID 37596525, 2023). "The HIV-related aspects considered were: Viral Load (VL), CD4+ cell count, opportunistic infections, and genotype testing." (PMID 36870111, 2023). "For those with advanced HIV prior to the start of ART (e.g., low CD4 nadir, prior opportunistic infection), the improvement usually seen in the CD4:CD8 ratio is minor." (PMID 36851599, 2023). "Prophylaxis against opportunistic infections: Out of the 18 patients with a CD4 count of less than 200 cells/mm3, only eight (44.4%) received co-trimoxazole as either prophylaxis or treatment." (PMID 38633911, 2023). "When the CD4 T-lymphocyte count fell below 500 cells/μL in stages 2 and 3 of infection (15.79% and 31.58%, respectively), several opportunistic infections were discovered." (PMID 37763724, 2023). "The association between low Hb values with low CD4 T lymphocyte count and high frequency of CMV co-infection suggests that anemia can be caused by advanced HIV with opportunistic infections such as TB and/or CMV." (PMID 37143662, 2023).